TUBAL3 (tubulin alpha like 3)
Description:
Tubulin is the major constituent of microtubules, a cylinder consisting of laterally associated linear protofilaments composed of alpha- and beta-tubulin heterodimers. Microtubules grow by the addition of GTP-tubulin dimers to the microtubule end, where a stabilizing cap forms. Below the cap, tubulin dimers are in GDP-bound state, owing to GTPase activity of alpha-tubulin.
Synonyms: FLJ21665
Tractability: Small molecule: a high-quality ligand is known; it belongs to a druggable protein family. PROTAC: ubiquitination databases record sites on it; its protein half-life has been measured; a small molecule that binds it is known.
Gene: Protein-coding gene on chromosome 10 (5,393,101 to 5,404,828, reverse strand). Ensembl gene ENSG00000178462.
Subcellular location: Cytoplasm, cytoskeleton
Pathways (Reactome):
Cell Cycle: EML4 and NUDC in mitotic spindle formation; Mitotic Prometaphase; Recruitment of NuMA to mitotic centrosomes; Resolution of Sister Chromatid Cohesion; Sealing of the nuclear envelope (NE) by ESCRT-III; Separation of Sister Chromatids; The role of GTSE1 in G2/M progression after G2 checkpoint
Vesicle-mediated transport: COPI-dependent Golgi-to-ER retrograde traffic; COPI-independent Golgi-to-ER retrograde traffic; COPI-mediated anterograde transport; Gap junction assembly; Microtubule-dependent trafficking of connexons from Golgi to the plasma membrane; Translocation of SLC2A4 (GLUT4) to the plasma membrane
Metabolism of proteins: Carboxyterminal post-translational modifications of tubulin; Formation of tubulin folding intermediates by CCT/TriC; Post-chaperonin tubulin folding pathway
Immune System: MHC class II antigen presentation; PKR-mediated signaling
Neuronal System: Activation of AMPK downstream of NMDARs; Assembly and cell surface presentation of NMDA receptors
Signal Transduction: RHO GTPases Activate Formins; RHO GTPases activate IQGAPs
Autophagy: Aggrephagy
Cellular responses to stimuli: HSP90 chaperone cycle for steroid hormone receptors (SHR) in the presence of ligand
Developmental Biology: Recycling pathway of L1
Disease: HCMV Early Events
Hemostasis: Kinesins
Organelle biogenesis and maintenance: Cargo trafficking to the periciliary membrane
Gene Ontology:
Molecular function: GTP binding; GTPase activity; structural constituent of cytoskeleton
Biological process: mitotic cell cycle; cytoskeleton organization; microtubule-based process
Cellular component: cytoskeleton; microtubule
Genetic constraint (gnomAD): Loss-of-function variants: 11 observed, 12.43 expected, observed/expected ratio (o/e) 0.88, 90% interval 0.56 to 1.46. The upper end of that interval is the gene's LOEUF score, 1.46, which puts it in group 6 of 6, group 1 being the genes least tolerant of losing a copy. Missense variants: 379 observed, 363.18 expected, observed/expected ratio (o/e) 1.04, 90% interval 0.96 to 1.14. Synonymous variants: 129 observed, 137.17 expected, observed/expected ratio (o/e) 0.94, 90% interval 0.81 to 1.09.
Homologues: Orthologues: chimpanzee TUBAL3 (99% identical), macaque TUBAL3 (96% identical), rabbit TUBAL3 (85% identical), dog TUBAL3 (84% identical), mouse Tubal3 (83% identical), rat Tubal3 (82% identical), pig TUBAL3 (81% identical). Paralogues in human: TUBA1B (74% identical), TUBA1A (74% identical), TUBA4A (74% identical), TUBA1C (73% identical), TUBA3C (73% identical), TUBA3D (73% identical), TUBA3E (72% identical), TUBA8 (72% identical), TUBB3 (39% identical), TUBB1 (39% identical), TUBB (39% identical), TUBB4B (39% identical), and 11 more.
Diseases named in the same sentence as TUBAL3 in open-access papers:
TUBAL3 is named in the same sentence as 5 diseases in open-access papers, as found by Europe PMC text mining. Sharing a sentence is not in itself a finding about the gene and the disease. The quoted sentences say what the papers report.
lung carcinoma (1 paper, 2024). "A network of interactions between proteins TUBB2B, MAPK7, TUBAL3, MAP2K5, and GJA1 (Cx43) suggests that reduced expression of MAPK and tubulin genes could be responsible for the attenuation of the gap junction pathway and insensitivity of lung cancer cells to cisplatin." (PMID 38351531, 2024).
infection (1 paper, 2023). The state of being infected such as from the introduction of a foreign agent such as serum, vaccine, antigenic substance or organism. "Among them, eight DEGs (RF00100, NXPH2, SEC61G, GADD45G, TUBAL3, LIPE, CSRNP1, and FAM20A) were shared across different comparison groups after FX0910 infection." (PMID 37982609, 2023).
TUBAL3 also shares sentences with these, for which no sentence is quoted: bacterial infection (1 paper); esophageal squamous cell carcinoma (1); tumor (1).